FOXO1 (forkhead box O1)
Diseases named in the same sentence as FOXO1 in open-access papers (continued):
Sharing a sentence is not in itself a finding about the gene and the disease.
melanoma (21 papers, 2012 to 2025). A malignant, usually aggressive tumor composed of atypical, neoplastic melanocytes. "PUMA is a FOXO1/3a target which is strongly induced in presence of genotoxic stress and is implicated in the induction of apoptosis in melanoma." (PMID 24970815, 2014). "We also found that resveratrol enhanced the susceptibility of melanoma to the cytotoxicity of IL-2-activated killer cells, and induced the expression of the tumor suppressor gene FoxO1." (PMID 22532866, 2012). "InSKCM, correlations between FOXO1 expression and melanoma Clark level, Breslowdepth, pathologic T stage, and melanoma ulceration were observed." (PMID 38716982, 2024). "Together, these results indicated that RSK2 increases cyclin D1 by promoting FOXO1 degradation in melanoma cells." (PMID 36210843, 2022). "Taken together, our results revealed that FOXO1 is a novel RSK2 substrate and discovered a new RSK2–FOXO1–cyclin D1 cascade involved in melanoma cell proliferation." (PMID 36210843, 2022). "Mechanistically, RSK2 enhances the phosphorylation of FOXO1 by interacting with FOXO1 and promoting its subsequent degradation, leading to upregulation of cyclin D1 in melanoma cells." (PMID 36210843, 2022). "Our results reveal that RSK2 not only promotes melanoma cell proliferation, but also mediates vemurafenib resistance through the upregulation of cyclin D1 mediated by accelerating the degradation of FOXO1 by phosphorylation." (PMID 36210843, 2022). "Together, we have uncovered a new mechanism RSK2-mediated phosphorylation and stabilization of FOXO1, thereby increasing cyclin D1 expression, is involved in promotion of melanoma cell proliferation." (PMID 36210843, 2022). "For example, a study indicated that miRNA-135a promotes cell proliferation, tumorigenicity, and cell cycle progression by transcriptionally downregulating FoxO1 in malignant melanoma cells." (PMID 34418600, 2021). "Next, we analyzed the expression profiles of USP7, EZH2 and FOXO1 in human samples from histologically normal skin tissues in tumor-adjacent regions, nevus, malignant melanoma and metastatic melanoma." (PMID 33849069, 2021). "FoxO1 and FoxO3a-mediated anti-melanoma activities are also derived from the regulation of miRNAs, including miRNA-135a, miRNA-182, and miRNA-194." (PMID 34418600, 2021). "Colony formation assays showed that USP7 or EZH2 depletion hampered the colony formation of melanoma A375 cells, which was also rescued, to some extent, by knockdown of FOXO1." (PMID 33849069, 2021). "For example, in melanoma cells mir-135a is upregulated resulting in downregulation of the forkhead box O 1(FoxO1) protein, a transcription factor known for its tumor suppressor role." (PMID 29268774, 2017). "To this end, we resected the primary melanoma in the skin and examined the transcripts of FoxO1 by QPCR." (PMID 22532866, 2012). "We next investigated how RSK2 regulates FOXO1 expression in melanoma cells." (PMID 36210843, 2022). "Studies showed that FoxO1 and FoxO3a are a target of regulation by melanoma-related miRNAs." (PMID 34418600, 2021). "Thus, USP7 recruiting PRC2 complex to suppress the expression of FOXO1 can protect melanin tumors from chemical toxicity, thus promoting the progression of melanoma." (PMID 33849069, 2021). "Treatment of these cells with different doses of the chemotherapy drugs (BRAF inhibitor), dabrafenib or vemurafenib, used in melanoma treatment revealed that USP7- or EZH2-deficient cells were more sensitive to chemotherapeutics, which could be partially rescued by FOXO1 knockdown." (PMID 33849069, 2021). "In human and canine melanoma cells, 5-aza promotes apoptosis by upregulating the mRNA expression of the tumor necrosis factor-alpha (TNF-α) via the activation of FoxO1 resulting from the inactivation of Akt." (PMID 34418600, 2021).
melanoma (continued). "We also discovered a novel functional characteristic of resveratrol in induction of suppressive activity of MDSC and expression of FoxO1 transcripts in context of suppressing the development of VLS and the growth and metastasis of B16F10 melanoma." (PMID 22532866, 2012). "In this work, we found that knockdown of RSK2 in melanoma cells did not affect FOXO1 mRNA expression but increased its protein level." (PMID 36210843, 2022). "The IHC staining and the quantitation analysis revealed that compared to the normal skin tissue, USP7 and EZH2 were highly expressed but FOXO1 was expressed at a lower level in melanoma samples, and the expression levels of USP7 with EZH2 or FOXO1 were correlated with cancer progression." (PMID 33849069, 2021).
depression (19 papers, 2017 to 2025). "In the chronic social stress defeat model of depression, low endothelial levels of FoxO1 and HDAC1 are associated with stress resilience." (PMID 33139732, 2020). "All of these facts indicate that the inhibitory expression of FoxO1 is associated with depression." (PMID 32532322, 2020). "Finally, we generated mice with conditional BDNF deletion in the mPFC and determined the impact of BDNF loss on depression-related behaviors and FoxO1 expression in mPFC." (PMID 32532322, 2020). "FOXO1 is highly expressed in brain regions associated with mood and stress regulation, and mice deficient in FOXO1 exhibit depression‐like behavior, suggesting that FOXO1 may take part in the pathological process of depression." (PMID 40237232, 2025). "Previous reports have shown that the SIRT1/FOXO1 axis contributes to hippocampal angiogenesis in depression treatment and facilitates wound healing in diabetic models." (PMID 40025506, 2025). "Considerable evidence has proven that the expression of FOXO1 is manipulated by phosphorylation during depression." (PMID 40102990, 2025). "In vitro and in vivo experiments confirmed that KJG is an effective treatment for depression by downregulating TLR4 expression to reduce neuroinflammation through the PI3K/AKT/FOXO1 pathway." (PMID 37173696, 2023). "FoxO1, belonging to the FoxO subfamily is involved in the development of major depressive disorders." (PMID 32532322, 2020). "Reduced FoxO1 levels in the mPFC were also involved in depression-related behaviors of CUS-treated postpartum female mice." (PMID 32532322, 2020). "Overall, the findings suggest that KJG may have therapeutic potential for depression by targeting the PI3K/AKT/FOXO1 pathway and its potential regulation by TLR4." (PMID 37173696, 2023). "In addition to the PI3K/AKT inflammatory cascade, some protein candidates associated with susceptibility to stress-induced depression have been identified, including PTEN, FoxO1, and NF-κB." (PMID 37173696, 2023). "Taken together, our results suggest that PI3K/Akt/FoxO1 signaling may be involved in the pathophysiology of depression." (PMID 37308778, 2023). "Additionally, a study using a FoxO1 knockout mouse model suggested that FoxO1 KO mice displayed depression-like behaviors as indicated by behavioral despair in the FST and TST." (PMID 32532322, 2020). "Interestingly, FOXO1 was recently identified as a gene predictor of depression in gene × environment interactions taking into account early life traumatic experiences." (PMID 31974313, 2020). "Interestingly, FoxO1 was recently proposed as a novel gene predictor of depression in gene × environment interactions." (PMID 31974313, 2020). "Furthermore, we found that FoxO1 is also decreased in CUS-treated postpartum female mice with a significant correlation with depression-related behaviors." (PMID 32532322, 2020). "Our results suggest causal relations between microglial SIRT1 or FOXO1 and therapeutic activity of UB in depression‐related behaviors and/or cytotoxicity and provide more evidence to expand the powerful actions of SIRT1 in the pathology and treatment of depression." (PMID 40237232, 2025). "FOXO1, one of the FOXO transcription factors, was reported to be positively correlated with depression‐related behaviors in our and other studies." (PMID 40237232, 2025). "Therefore, we hypothesize that FOXO1-regulated microglia may potentially exacerbate brain damage and depression post-TBI while PI3K/Akt, TLR/NF-κB or AMPK/SIRT1 signaling pathways may interact with FOXO1 to regulate neutrophil activities in TBI requiring further investigation." (PMID 38556884, 2024). "Altogether, these findings revealed that dysregulated iron metabolism mediated by FOXO1 between neutrophils and oligodendrocytes results in a decrease in MBP in oligodendrocytes, thereby contributing to the development of depression following TBI." (PMID 38556884, 2024).
depression (continued). "We investigated the role of PTEN in regulating FoxO1‐ and TLR4‐mediated neuronal injury in mice with depression." (PMID 37308778, 2023). "Baicalin significantly reduced the levels of TNF-α, IL-1β, and IL-6 in depression-like hippocampal tissues by upregulating PI3K/AKT/FOXO1 pathway and inhibiting TLR4 expression and so alleviate neuroinflammation-induced depression-like behavior." (PMID 35350754, 2022). "FoxO1 is highly expressed in brain areas related to the regulation of mood and stress, and FoxO1-deficient mice show a depressive-like phenotype in forced swim test (FST) and tail suspension test (TST) behaviors assessments, which means FoxO1 may be involved in the pathology of depression." (PMID 32532322, 2020). "In the current investigation, we observed that UB exerted efficient therapeutic activities on depression‐like behaviors, suppressed microglia activation and neuroinflammation, balanced M1/M2 polarization, and restored the abnormal levels of SIRT1 and FOXO1 in the hippocampus." (PMID 40237232, 2025). "It indicates that modulating FOXO1 activity in neutrophils could be beneficial in attenuating TBI-induced brain damage and depression, paving the way for future therapeutic development." (PMID 38556884, 2024). "The correlation analysis revealed that there were significant positive or negative correlations between depression-related behavior and FoxO1 mRNA expression levels." (PMID 32532322, 2020). "Our findings also indicate that PPD female mice also showed decreased FoxO1 expression in the mPFC but not in the hippocampus and a significant correlation of FoxO1 expression with depression-related behaviors." (PMID 32532322, 2020). "UB efficiently alleviated depression‐related behaviors, accompanied by suppressed microglia activation, neuroinflammation, changes of classic activation (M1)/alternative activation (M2) polarization and recovered sirtuin‐1 (SIRT1) and forkhead box protein O1 (FOXO1) expression in the hippocampus." (PMID 40237232, 2025). "In order to elucidate the underlying molecular mechanisms by which FOXO1 regulates neutrophils in depression induced by TBI, we employed proteomics methods to analyze and compare the changes of protein in injured brain tissues of mice with or without TBI-induced depression." (PMID 38556884, 2024).
heart failure (19 papers, 2014 to 2025). Inability of the heart to pump blood at an adequate rate to meet tissue metabolic requirements. "SFYX is known to protect against heart failure by activating SIRT3/FOXO1 signaling-mediated mitophagy and apoptosis through deacetylation." (PMID 41567643, 2025). "Studies have shown that excessive activation of cardiac FoxO1 causes DCM and heart failure via insulin receptor substrate downregulation." (PMID 36843604, 2023). "FOXO1 is known to induce cardiac cell death and to promote heart failure following cardiomyopathy." (PMID 36143454, 2022). "Thus, it would be of interest to investigate if FOXO1 inhibition decelerates heart failure progression." (PMID 36143454, 2022). "Data reported here suggest that targeting FOXO1 by AS, by restoring balanced mitochondrial oxidative metabolism, may have the potential to be a promising treatment for heart failure and DCM." (PMID 32450616, 2020). "Heart failure in models overexpressing cardiac FoxO1 mimics heart failure in humans." (PMID 29484207, 2018). "FoxO1 null mice (at e9.5) have underdeveloped blood vessels, whereas overexpression of the FoxO1 gene (at e10.5) results in reduced heart size, myocardium thickening (myocardium thickening also results from transgene expression of FoxO1 at e18.5), and eventual heart failure." (PMID 29484207, 2018). "A decreased expression of FOXO1, as it has been found in the NIDCM cohort of this study, could be interpreted as a rescue mechanism to avoid an enormous loss of cardiac cell mass and to slow down heart failure progression." (PMID 36143454, 2022). "Thus, we see FOXO1 null mice have underdeveloped blood vessels, whereas overexpression of the FOXO1 gene results in reduced heart size, myocardium thickening, and eventual heart failure." (PMID 30423812, 2018). "Due to lower expression of Sirt1 and MnSOD in heart failure, translocation of transcriptional factor FoxO1, which could modulate the expression of MnSOD, was examined, Immunostaining revealed decreased FoxO1 in the nucleus in advanced heart failure cardiomyocytes." (PMID 24913149, 2014). "They reported that liraglutide significantly reduced the expression of both FOXO1 and MURF1, effectively reversing the progression of heart failure." (PMID 41373699, 2025). "First, the high-glucose environment upregulates the PI3K/Akt/FoxO1/LOXL2 pathway, leading to the development of myocardial fibrosis and then heart failure." (PMID 38883603, 2024). "Interestingly, both FOXO1 and MAPK14—another important node in our network—were also implicated in the development of heart failure, therefore the identified targets may reflect key regulating mechanisms in both atherosclerotic disease and heart failure." (PMID 28293796, 2017). "Although there is no direct clinical evidence of FoxO1 activation during DbCM, its DNA binding sites are overrepresented in the promoter sequences of heart failure genes in isolated RNA from the myocardium of heart failure patients with either ischemic or idiopathic dilated cardiomyopathy." (PMID 39206323, 2024).
periodontitis (19 papers, 2014 to 2025). An acute or chronic inflammatory process that affects the tissues that surround and support the teeth. "In summary, we showed that FOXO1 is generally underexpressed in patients with periodontitis and that FOXO1 expression is associated with the osteogenic differentiation process of PDLSCs." (PMID 37644500, 2023). "The reciprocal action of STAT3 and FOXO1 on ITGB6 downregulation was also confirmed by the immunostaining of the inflammatory epithelium associated with periodontitis." (PMID 36299623, 2022). "Furthermore, the reciprocal action of STAT3 and FOXO1 on ITGB6 downregulation was also confirmed by the immunostaining of the inflammatory epithelium associated with periodontitis." (PMID 36299623, 2022). "Interestingly, reduced DC homing to lymph nodes and periodontal tissues caused by lineage specific Foxo1 deletion in DCs increases periodontal inflammation and susceptibility to periodontitis." (PMID 31849924, 2019). "Upon differentiation of periodontitis PDLSCs, FOXO1 gene was increased and competitively bind β-catenin to inhibit the canonical Wnt/β-catenin." (PMID 39959357, 2025). "In consistent with this, the salivary level of FOXO1 was negatively correlated with that of 8‐OHdG, a marker of the oxidative stress, in periodontitis patients, suggesting the role of FOXO1 in supporting the antioxidant defense." (PMID 40989573, 2025). "On one hand, patients suffered from periodontitis had a low expression of FOXO1 and the combination of FOXO1 to METTL3 regulates PDLSCs to promote osteogenesis through the PI3K/AKT signaling pathway." (PMID 39974190, 2025). "MiRNA-182 targeted FOXO1 gene leading to decrease of osteogenic differentiation in periodontitis PDLSC." (PMID 39959357, 2025). "This study aims to determine FOXO1 and 8-OHdG levels in serum and saliva samples of periodontitis patients and to evaluate their relationship with clinical periodontal parameters." (PMID 38658396, 2024). "The salivary FOXO1 levels were significantly lower in both periodontitis groups compared to the control group." (PMID 38658396, 2024). "According to our results, the oxidative stress (8-OHdG)/antioxidant (FOXO1) ratio in patients with periodontitis varies in favor of oxidative stress compared to the healthy group." (PMID 38658396, 2024). "In the current study, salivary FOXO1 levels were statistically significantly lower in periodontitis groups than in the control group." (PMID 38658396, 2024). "More in vitro and in vivo studies are needed to ensure the role of FOXO1 in promoting tissue regeneration in periodontitis, the immune system, and osteogenesis." (PMID 38658396, 2024). "Salivary FOXO1 levels were statistically significantly decreased in the periodontitis groups compared to the control group." (PMID 38658396, 2024). "In subsequent studies, examining the behavior of FOXO1 in different stages of periodontitis will highlight the intricate nature of FOXO." (PMID 38658396, 2024). "While salivary 8-OHdG level was statistically significantly higher in periodontitis groups, salivary FOXO-1 level was significantly lower." (PMID 38658396, 2024). "Our research indicated that targeting FOXO1 to promote the osteogenic differentiation of PDLSCs is a potential method for the treatment and prevention of periodontitis." (PMID 37644500, 2023). "To investigate the abnormal expression and role of the transcription factor FOXO1 in periodontitis, we tested the expression of FOXO1 in clinical samples from patients with periodontitis." (PMID 37644500, 2023). "The expression of FOXO1 changed with the osteogenic differentiation of PDLSCs in patients with periodontitis." (PMID 37644500, 2023). "The expression of FOXO1 in the clinical samples of the periodontitis group was significantly lower than that in the normal group." (PMID 37644500, 2023).